PCBD2 (pterin-4 alpha-carbinolamine dehydratase 2)
Description:
Plays a role in tetrahydrobiopterin biosynthesis which is a co-factor for amino acid hydroxylases. May prevent both the formation of 7-pterins and accelerate the formation of quinonoid-BH2 (By similarity). Regulates the dimerization of homeodomain protein HNF1A and enhances its transcriptional activity. Also acts as a coactivator for HNF1B-dependent transcription.
Synonyms: DCOH2; DCOHM; PHS2
Tractability: Antibody: the Human Protein Atlas places it where antibodies can reach. PROTAC: its protein half-life has been measured.
Gene: Protein-coding gene on chromosome 5 (134,905,114 to 135,007,959, forward strand). Ensembl gene ENSG00000132570.
Subcellular location: Nucleus; Cytoplasm
Subcellular location (Human Protein Atlas): Plasma membrane
Gene Ontology:
Molecular function: protein binding; 4-alpha-hydroxytetrahydrobiopterin dehydratase activity
Biological process: positive regulation of DNA-templated transcription; tetrahydrobiopterin biosynthetic process
Cellular component: mitochondrion; cytoplasm; nucleus
Genetic constraint (gnomAD): Loss-of-function variants: 10 observed, 13.01 expected, observed/expected ratio (o/e) 0.77, 90% interval 0.47 to 1.3. The upper end of that interval is the gene's LOEUF score, 1.3, which puts it in group 5 of 6, group 1 being the genes least tolerant of losing a copy. Missense variants: 125 observed, 134.65 expected, observed/expected ratio (o/e) 0.93, 90% interval 0.8 to 1.08. Synonymous variants: 50 observed, 51.58 expected, observed/expected ratio (o/e) 0.97, 90% interval 0.77 to 1.23.
Homologues: Orthologues: chimpanzee PCBD2 (98% identical), macaque PCBD2 (90% identical), dog PCBD2 (75% identical), mouse Pcbd2 (69% identical), guinea pig PCBD2 (65% identical), tropical clawed frog pcbd2 (62% identical), Caenorhabditis elegans pcbd-1 (48% identical), Drosophila melanogaster Pcd (41% identical). Paralogues in human: PCBD1 (48% identical).
Diseases named in the same sentence as PCBD2 in open-access papers:
PCBD2 is named in the same sentence as 9 diseases in open-access papers, as found by Europe PMC text mining. Sharing a sentence is not in itself a finding about the gene and the disease. The quoted sentences say what the papers report.
rectal cancer (3 papers, 2020 to 2025). A primary or metastatic malignant neoplasm that affects the rectum. "PCBD2 is a target of the microRNA miR-3174, with this miRNA potentially having a role in rectal cancer through its action on PCB2." (PMID 32727510, 2020). "It was also mentioned that the targeting of PCBD2 factor by miR-3174 may play an oncogenic role in the development of rectal cancer, which prompted our subsequent consideration of the downstream targets of miR-3174." (PMID 39641247, 2024). "PCBD2, though previously studied in rectal cancer, may have tumor-suppressive potential in LUAD." (PMID 40722386, 2025).
preeclampsia (1 paper, 2025). Preeclampsia is a hypertensive disorder of pregnancy that is characterized by new-onset hypertension with proteinuria presenting after 20 weeks of gestation, and depending on mild or severe forms may initially present with severe headache, visual disturbances, and hyperreflexia. "PCBD2, a key enzyme in L-phenylalanine metabolism, exhibited decreased expression in preeclampsia cases." (PMID 40061129, 2025).
prostatitis (1 paper, 2025). An infectious or non-infectious inflammatory process affecting the prostate gland. "Our analysis revealed two Tier 2 genes (NOA1 and ELAC2) for BPH, two Tier 3 genes (TRMU and SFXN5) for prostatitis, and six Tier 3 genes (MRPL24, NDUFS6, PUS1, NBR1, GLOD4, and PCBD2) for PCa." (PMID 40919435, 2025). "We revealed two Tier 2 genes (NOA1 and ELAC2) and one Tier 3 gene (ACAT1) for BPH, two Tier 3 genes (TRMU and SFXN5) for prostatitis, and six Tier 3 genes (MRPL24, NDUFS6, PUS1, NBR1, GLOD4, and PCBD2) for PCa." (PMID 40919435, 2025).
type II diabetes (1 paper, 2023). "According to Tholen, the PCBD2 gene is abundant in adipose tissue and is associated with type II diabetes." (PMID 37686221, 2023).
cancer (2 papers, 2010 to 2021). A tumor composed of atypical neoplastic, often pleomorphic cells that invade other tissues. "Of interest, over half of these regions (9/14, 64%) included genes that are of known significance in cancer such as the DHFR gene, whose product may confer methotrexate resistance, and the PCBD2 gene, which is a co-factor for TCF1." (PMID 20485525, 2010).
PCBD2 also shares sentences with these, for which no sentence is quoted: tumor (3 papers); allergic asthma (1); colorectal cancer (1); hepatoma (1).